MILIP (MYC inducible lncRNA inactivating p53)
Synonyms: MAFG-AS1; MAFG-DT
Gene: Long non-coding RNA gene on chromosome 17 (81,927,829 to 81,930,753, forward strand). Ensembl gene ENSG00000265688.
Diseases named in the same sentence as MILIP in open-access papers:
MILIP is named in the same sentence as 14 diseases in open-access papers, as found by Europe PMC text mining. Sharing a sentence is not in itself a finding about the gene and the disease. The quoted sentences say what the papers report.
clear cell renal cell carcinoma (3 papers, 2023 to 2025). "In another study, lncRNA MILIP was shown to bind YBX1, affecting Snail translation and promoting renal clear cell carcinoma metastasis." (PMID 40234937, 2025). "The lncRNA MILIP bound with YBX1 to increase the translation of Snail, leading to the enhanced metastasis of clear cell renal cell carcinoma cells." (PMID 38491348, 2024).
breast carcinoma (2 papers, 2020 to 2024). "This study identified 11 key methylation-driven lncRNAs (DIO3OS, ELOVL2-AS1, MIAT, LINC00536, C9orf163, AC105398.1, LINC02178, MILIP, HID1-AS1, KCNH1-IT1, and TMEM220-AS1) closely associated with breast cancer prognosis through three machine learning methods." (PMID 39456830, 2024). "Instructively, MILIP expression was increased in cancer versus normal cell lines as shown in comparisons between human MDA-MB-231 breast cancer and U2OS osteosarcoma cells in addition to A549, HCT116, and MCF-7 cells compared with MCF10A and HME-1 cell lines." (PMID 33020477, 2020).
lung adenocarcinoma (2 papers, 2020 to 2022). A carcinoma that arises from the lung and is characterized by the presence of malignant glandular epithelial cells.
neuroblastoma (2 papers, 2022 to 2025). Neuroblastoma (NB) is the most common solid, extracranial childhood tumor. "The effect of MILIP knockdown was associated with the accumulation of DNA DSBs in neuroblastoma cells largely due to decreased activity of the NHEJ DNA repair pathway." (PMID 36445966, 2022). "High MILIP expression was associated with poor outcome and appeared as an independent prognostic factor in neuroblastoma patients." (PMID 36445966, 2022). "Cursory screening of neuroblastoma cell lines showed that MILIP levels were also positively associated with N-Myc protein levels." (PMID 36445966, 2022). "Targeted inhibition of MILIP enhances the in vivo growth inhibitory effect of cisplatin on neuroblastoma." (PMID 41244073, 2025). "We investigated the potential of MILIP in regulating neuroblastoma cell sensitivity to ionizing radiation (IR) and cisplatin (CDDP), which are commonly used for neuroblastoma treatment and known to exert therapeutic effects mainly through DSBs." (PMID 36445966, 2022). "Intriguingly, Ku70 and Ku80 are highly abundant proteins with approximately 500,000 molecules per cell, whereas MILIP, like many other lncRNAs, is expressed at noticeably lower abundance, with approximately 128–286 molecules per neuroblastoma cell." (PMID 36445966, 2022). "Here, we report that the lncRNA MILIP is transcriptionally regulated by N-Myc and functions to promote DNA double-strand break repair in neuroblastoma cells." (PMID 36445966, 2022). "MILIP expression is frequently increased in neuroblastoma and is potentially an independent prognostic factor for patients." (PMID 36445966, 2022). "Cotransfection of MILIP mutants carrying mismatches in the targeting sequences rescued the cells, validating the specificity of the Gapmers and further consolidating the role of MILIP in promoting neuroblastoma cell survival and proliferation." (PMID 36445966, 2022). "The effect of MILIP knockdown on neuroblastoma cell viability was also evident in clonogenic assays." (PMID 36445966, 2022). "To further understand the mechanism responsible for MILIP-mediated promotion of neuroblastoma cell survival and proliferation, we analyzed the proteins that interact with MILIP using RNA pulldown (RPD) followed by mass spectrometry." (PMID 36445966, 2022). "Using in situ hybridization (ISH) analysis, we confirmed that MILIP was readily detected in neuroblastoma cells with primarily nuclear localization in human neuroblastoma tissues." (PMID 36445966, 2022). "Consistently, along with Ku70 and Ku80, other key components of the NHEJ complex, namely DNA ligase 4 and XRCC4, were recovered with MILIP in neuroblastoma cells." (PMID 36445966, 2022). "This correlative relationship between MILIP and N-Myc mRNA was similarly observed in additional neuroblastoma datasets." (PMID 36445966, 2022). "Knockdown of MILIP reduced neuroblastoma cell viability through the induction of apoptosis and inhibition of proliferation, retarded neuroblastoma xenograft growth, and sensitized neuroblastoma cells to DNA-damaging therapeutics." (PMID 36445966, 2022). "To further examine the therapeutic potential of MILIP targeting in the treatment of neuroblastoma, we employed Gapmers against MILIP." (PMID 36445966, 2022). "Therefore, high MILIP expression in neuroblastoma tissues is potentially an independent prognostic factor of patient outcome." (PMID 36445966, 2022). "Moreover, revealing the therapeutical potential of targeting MILIP, we establish its cooperation with genotoxic stress to inhibit neuroblastoma growth in vivo." (PMID 36445966, 2022). "Thus, MILIP plays a role in promoting neuroblastoma cell survival, proliferation, and tumorigenicity." (PMID 36445966, 2022).
neuroblastoma (continued). "Our results clearly demonstrate that MILIP promotes neuroblastoma development and progression." (PMID 36445966, 2022). "Collectively, our findings identify MILIP as an N-Myc downstream effector critical for activation of the NHEJ DNA repair pathway in neuroblastoma cells, with practical implications of MILIP targeting, alone and in combination with DNA-damaging therapeutics, for neuroblastoma treatment." (PMID 36445966, 2022). "Together, these results substantiate the role of MILIP in promoting NHEJ in neuroblastoma cells." (PMID 36445966, 2022). "Nuclear localization of MILIP was also observed in cultured neuroblastoma cells." (PMID 36445966, 2022). "Similarly, when the high-quartile MILIP expression was used as the cutoff point, high MILIP levels were associated with poor PFS and OS of patients in the human neuroblastoma tissue gene expression Versteeg dataset." (PMID 36445966, 2022). "Thus, MILIP targeting represents a potential avenue for the development of improved neuroblastoma treatment." (PMID 36445966, 2022). "Disrupting the interaction between MILIP and Ku70 or Ku80 increased DNA DSBs and reduced cell viability with therapeutic potential revealed where targeting MILIP using Gapmers cooperated with the DNA-damaging drug cisplatin to inhibit neuroblastoma growth in vivo." (PMID 36445966, 2022). "Therefore, MILIP knockdown-induced DNA DSBs are not closely associated with unresolved TRCs in neuroblastoma cells." (PMID 36445966, 2022). "Therefore, N-Myc transcriptionally activates MILIP through the Myc-BR in neuroblastoma cells." (PMID 36445966, 2022). "Thus, MILIP expression contributes to neuroblastoma resistance to DNA-damaging therapeutics." (PMID 36445966, 2022). "In accordance, MILIP was expressed at higher levels in MYCN-amplified than MYCN-nonamplified neuroblastomas." (PMID 36445966, 2022). "Regardless, that MILIP facilitates the Ku70–Ku80 association is not in dispute and its action appears sufficient to activate the NHEJ pathway in neuroblastoma cells." (PMID 36445966, 2022). "Here, we show that MILIP, an N-Myc-responsive lncRNA, promotes the NHEJ pathway through facilitating Ku70–Ku80 heterodimerization and is involved in the resistance to DNA-damaging therapeutics in neuroblastoma cells." (PMID 36445966, 2022). "Therefore, binding to Ku70 and Ku80 is essential for MILIP to promote DSB DNA repair and cell survival and proliferation in neuroblastoma." (PMID 36445966, 2022). "Therefore, as the transcription factor that drives MILIP expression, N-Myc appears to have a unique role in the activation of NHEJ in neuroblastoma cells." (PMID 36445966, 2022). "In this study, we demonstrated that the N-Myc-responsive lncRNA MILIP functions as an RNA scaffold that facilitates Ku70–Ku80 heterodimerization to promote the NHEJ pathway, thus substantiating the role of N-Myc in regulating DNA DSB repair in neuroblastoma cells." (PMID 36445966, 2022). "However, while MILIP knockdown reduced the Ku70–Ku80 interaction, it did not affect Ku70 and Ku80 expression, suggesting that dimerization may not be an absolute requirement for K70 and Ku80 expression in neuroblastoma cells." (PMID 36445966, 2022).
adenoma (1 paper, 2020). A neoplasm arising from the epithelium. "Indeed, MILIP expression was increased in pre-neoplastic colon lesions (adenomas) compared with normal colon epithelia." (PMID 33020477, 2020).
colon cancer (1 paper, 2020). "Similarly, MILIP was upregulated in cohorts of non-small cell lung carcinoma and colon cancer tissues compared with paired adjacent normal epithelial tissues." (PMID 33020477, 2020).
metastatic tumors (1 paper, 2022). "Analysis of the ccRCC cell line dataset of the Cancer Cell Line Encyclopedia (CCLE) revealed that MILIP was expressed at higher levels in ccRCC cell lines generated from metastatic tumors compared with those from primary tumors." (PMID 36028903, 2022).
cancer (4 papers, 2020 to 2024). A tumor composed of atypical neoplastic, often pleomorphic cells that invade other tissues. "Akin to c-Myc, high MILIP expression was associated with poor overall survival (OS) in various cancer types, supporting the notion that MILIP upregulation contributes to c-Myc-driven cancer maintenance and progression." (PMID 33020477, 2020). "In support, MILIP expression levels correlated with MYC gene expression in diverse human cancer types." (PMID 33020477, 2020). "MILIP upregulation is observed amongst diverse cancer types and is shown to support cell survival, division and tumourigenicity." (PMID 33020477, 2020). "Similar to previous results in other types of cancer cells, MILIP was predominantly located to the cytoplasm in ccRCC cells as shown by qPCR analysis of subcellular fractions and in situ hybridization (ISH) analysis of Caki-1 and ACHN cells grown on coverslips." (PMID 36028903, 2022). "Among them was MILIP that is activated by c-Myc in other types of cancers." (PMID 36445966, 2022). "MILIP is transcriptionally activated by c-Myc in some other types of cancer cells." (PMID 36028903, 2022). "Moreover, we show that MILIP is commonly upregulated across diverse cancer types and is critical for cancer cell survival, division and tumourigenicity, with practical implications of targeting MILIP as a therapeutic avenue for cancer treatment." (PMID 33020477, 2020). "We, therefore, set to investigate whether MILIP is indeed regulated by c-Myc and whether it is involved in cancer pathogenesis." (PMID 33020477, 2020). "SiRNA silencing of MILIP inhibited cell viability in diverse types of cancer cell lines." (PMID 33020477, 2020). "Nevertheless, our results from studies using human cell line models and pre-malignant tissues suggest that MILIP may contribute to c-Myc-driven neoplastic transformation, and MILIP may therefore represent a potential anti-cancer target for counteracting the c-Myc-axis." (PMID 33020477, 2020). "Thus, MILIP expression is driven by c-Myc in a range of cancer cell types." (PMID 33020477, 2020). "Although the proto-oncoprotein c-Myc transcriptionally activates MILIP in many types of cancer cells, it did not regulate MILIP expression in ccRCC cells, suggesting that MILIP is regulated through a different transcriptional mechanism." (PMID 36028903, 2022). "However, the lack of similarity between human MILIP and Mus musculus transcripts makes it infeasible to test the role of MILIP in cancer initiation in transgenic mouse models." (PMID 33020477, 2020). "Noticeably, p14ARF mRNA but not MILIP levels correlate with MYC gene expression in normal human tissues 62, whereas MILIP is upregulated and its expression is positively associated with the levels of MYC expression in human cancers." (PMID 33020477, 2020).
MILIP also shares sentences with these, for which no sentence is quoted: tumor (2 papers); B-cell lymphoma (1); bladder cancer (1); non-small cell lung carcinoma (1); osteosarcoma (1); ovarian tumors (1).